WNT5B (Wnt family member 5B)
Diseases named in the same sentence as WNT5B in open-access papers (continued):
Sharing a sentence is not in itself a finding about the gene and the disease.
type 2 diabetes (9 papers, 2005 to 2023). "This CpG site can be mapped to the transcription start site of the WNT5B gene, which has been associated with adipogenesis, insulin secretion, and type 2 diabetes." (PMID 38201877, 2023). "To examine potential functionality of the main hit we ran several analyses, after annotating the CpG and finding that it maps to the transcription start site of the WNT5B gene, known to be associated with adipogenesis, insulin secretion, and type 2 diabetes." (PMID 35236238, 2022). "A case-control association study showed that SNP rs2270031, located in a WNT5B intron, is strongly associated with type 2 diabetes mellitus (T2DM) in a Japanese population." (PMID 34017835, 2021). "Disrupted WNT5B signaling leads to the progression of diseases such as osteoarthritis, osteoporosis, obesity, type 2 diabetes mellitus and chronic diseases associated with aging, as well as cancers." (PMID 34017835, 2021). "The first suggestion for a role of Wnt signaling in the pathogenesis of type 2 diabetes came from a study which reported a single nucleotide polymorphism locus in the Wnt5b gene that confered susceptibility to type 2 diabetes in a Japonese population." (PMID 20041157, 2009). "Wnt5b, for example, has recently been identified as a candidate gene for conferring susceptibility to type 2 diabetes." (PMID 16246260, 2005). "Indeed previously, overexpression of WNT5B was associated with increased adipogenesis in adipocytes, suggesting a role in type 2 diabetes development." (PMID 35236238, 2022). "Moreover, this CpG is located in the transcription start site of the WNT5B gene, known to be associated with adipogenesis, insulin secretion, and type 2 diabetes, which could represent a potential biological mechanism via DNA methylation." (PMID 35236238, 2022). "Expression of WNT5B gene was increased at an early phase of adipocyte differentiation in mouse and involved in the pathogenesis of the type 2 diabetes through the regulation of adipocyte function." (PMID 23805208, 2013). "This region is linked to type 1 diabetes mellitus, whereas single nucleotide polymorphisms in WNT5b and LRP5 genes may contribute to susceptibility to type 2 diabetes mellitus (T2DM) and obesity." (PMID 36947076, 2023). "We also highlight aberrances in non-canonical WNT5B signaling contributing to diseases such as osteoarthritis, osteoporosis, obesity, type 2 diabetes mellitus, neuropathology, and chronic diseases associated with aging, as well as various cancers." (PMID 34017835, 2021). "Moreover there was an overexpression of WNT5b, a gene found to be involved in adipogenesis and type 2 diabetes." (PMID 25799240, 2015). "Moreover, the presence of this TFBS cluster in human Wnt5b, absent in that of the rodents (mouse and rat), not only explains the observed human-rodents divergence of Wnt5b promoters, but also agrees with its implication in human type 2 diabetes." (PMID 20684756, 2010). "Also WNT5b seems to be involved in the pathogenesis of type 2 diabetes, even if this is not fully elucidated." (PMID 25799240, 2015).
osteosarcoma (7 papers, 2012 to 2025). A usually aggressive malignant bone-forming mesenchymal neoplasm, predominantly affecting adolescents and young adults. "Through analysis of osteosarcoma cell lines and stem cell spheres isolated from patients, it was found that WNT5B is highly expressed in osteosarcoma stem cells." (PMID 40665579, 2025). "We found that WNT5B is the most abundant WNT expressed in osteosarcoma tumours and its expression correlates with metastasis, histologic subtype and reduced survival." (PMID 38689429, 2024). "Recent work has highlighted the importance of WNT5B signaling in osteosarcomas, reigniting the interest in targeting WNT signaling in osteosarcomas." (PMID 39102216, 2024). "WNT5B expression is high in osteosarcoma stem cells and the addition of recombinant WNT5B to sarcospheres in vitro led to increased sphere size (an indication of cancer stem cells) and increased chemoresistance to methotrexate." (PMID 39102216, 2024). "In vivo, WNT5B increased osteosarcoma lung and liver metastasis and inhibited the glycosaminoglycan hyaluronic acid via upregulation of hyaluronidase 1 (HYAL1), leading to changes in the tumour microenvironment." (PMID 38689429, 2024). "In osteosarcoma cell lines and patient‐derived spheres, WNT5B is enriched in stem cells and induces the expression of the stemness gene SOX2." (PMID 38689429, 2024). "Together, these data define WNT5B's role in driving osteosarcoma cancer stem cell expansion and methotrexate resistance and provide evidence that the WNT5B pathway is a promising candidate for treating osteosarcoma patients." (PMID 38689429, 2024). "Future studies should test the inhibition of ROR1 in WNT5B-expressing osteosarcomas in vivo using Zilovertamab or a similar drug." (PMID 39102216, 2024). "WNT5B also has two different promoters and splice forms, suggesting the need to also investigate WNT5B isoforms in osteosarcoma." (PMID 34017835, 2021). "Out of the differentially modulated genes, those implicated in stem cell and osteosarcoma biology, such as PPARG, ETS1, WNT1, WNT5B, SOX2, NANOG, POU5F1, nestin, and ALDH were chosen for further analysis." (PMID 22870217, 2012). "WNT5B (WNT Family Member 5B) expression has been identified as high in osteosarcoma stem cells." (PMID 39154307, 2024). "Furthermore, we have shown that WNT5B inhibits normal osteoblast differentiation and it inversely correlates with osteoblast differentiation genes in osteosarcomas." (PMID 39102216, 2024). "Furthermore, WNT10B and WNT5B regulate different histological subtypes of osteosarcomas." (PMID 39102216, 2024). "In the osteosarcoma PeCan and TARGET datasets, WNT5B is expressed in 20 and 24% of tumors, respectively." (PMID 39102216, 2024). "We identified osteoblast differentiation genes (SP7 (osterix), ALPL, BMP4, and PHOSPHO1) in RNA-sequencing of osteosarcoma patient tumors and WNT10B correlated positively with these genes, while these genes inversely correlated with WNT5B." (PMID 39102216, 2024). "In osteosarcoma, it has been identified that the interaction of WNT5B and ROR2 can enhance cell migration, which supports a potential role of ROR2 and WNT5B in the metastatic pathway of osteosarcoma cells." (PMID 34017835, 2021). "Jude Children’s Research Hospital (p < 0.05, data not shown), and 23 osteosarcoma tumors from GEO dataset GSE36004 (p < 0.02, data not shown) revealed that WNT5B and WNT10B are not expressed in the same tumors." (PMID 39102216, 2024). "WNT5B, a β-catenin-independent ligand, and WNT10B, a β-catenin-dependent WNT ligand, are each expressed in osteosarcomas, but they are not expressed in the same tumors." (PMID 39102216, 2024).
chronic lymphocytic leukemia (5 papers, 2020 to 2023). "Wnt members, including Wnt3, Wnt4, Wnt5B, Wnt6, Wnt7B, Wnt9A, Wnt10A, Wnt14 and Wnt16, are highly expressed in chronic lymphocytic leukaemia B cells." (PMID 33417298, 2021). "Several groups have shown that WNT5B is significantly higher in chronic lymphocytic leukemia (CLL) than normal B cells." (PMID 34017835, 2021). "For instance, epigenetic inactivation of SERP genes allowed constitutive Wnt signaling pathway in colorectal cancer, while overexpression of Wnt genes (Wnt 3, Wnt5b, Wnt6, Wnt10a, Wnt14, and Wnt16) activated Wnt signaling pathway in Chronic lymphocytic leukemia." (PMID 32904598, 2020). "It has been shown that in B-cells of Chronic Lymphocytic Leukemia (CLL), mRNA related to Wnt elements is overexpressed, such as WNT3, WNT5B, WNT6, WNT10A, WNT14, WNT16 or FZD3." (PMID 37237497, 2023).
colorectal cancer (5 papers, 2014 to 2021). A primary or metastatic malignant neoplasm that affects the colon or rectum. "This specific WNT5B SNP is significant because it shows for the first time that a WNT polymorphism can predict early tumor recurrence in colorectal cancer, and suggests that more research needs to be done to understand the consequences of both the SNP and WNT5B in CRC." (PMID 34017835, 2021).
lung carcinoma (5 papers, 2019 to 2023). "WNT5B-associated exosomes promoted cancer progression in a paracrine manner, as seen in their ability to induce proliferation and migration on A549 lung cancer cells." (PMID 34017835, 2021). "Mechanistically, WNT5B was shown to regulate the metabolism of the lung cancer cells, including the amino acid transporter LAT1." (PMID 34017835, 2021). "Both WNT5A and WNT5B are expressed in the lung and have been implicated in lung pathogenesis, including COPD and lung cancer." (PMID 34017835, 2021). "WNT5B is up-regulated in MCF-7 cells and is associated with cell migration and proliferation in lung cancer cells." (PMID 31080560, 2019). "On the basis of its different roles in different cancers, Wnt5b may constitute a specific marker for lung cancer screening." (PMID 31130856, 2019). "Evidence has accumulated that both WNT-5A and WNT-5B are involved in the development and progression of chronic lung diseases, including asthma, IPF, lung cancer, and COPD." (PMID 31557955, 2019).
oral squamous cell carcinoma (5 papers, 2021 to 2024). "Interestingly, in oral squamous cell carcinoma, WNT5B has been shown to be upregulated in tumor cells when compared with normal tissue." (PMID 37971882, 2024). "Moreover, Slug is involved in the induction of Wnt5b in HSC-4 oral squamous cell carcinoma cells." (PMID 38141763, 2024). "Moreover, WNT5B depletion was shown to reduce lymph node metastases of oral squamous cell carcinoma cells, suggesting that WNT5B could be more broadly utilized by cancers to facilitate lymph node metastases." (PMID 37971882, 2024).
ovarian carcinoma (5 papers, 2016 to 2024). A malignant neoplasm originating from the surface ovarian epithelium. "WNT5B is important in ovarian cancer, particularly in ovarian cancer stem cells (OCSC)." (PMID 34017835, 2021). "While both WNT5B and WNT5A have been shown to be expressed in ovarian cancer, their functions are distinct." (PMID 34017835, 2021). "A previous study revealed that a Wnt5b orthologue Wnt5a suppress ovarian cancer cells, and our data revealed that Wnt5a showed relative higher expression in ovarian cancer cells than that of Wnt5b (data not shown)." (PMID 27072580, 2016). "Interestingly, Notch3 binding to the WNT5B promoter area has been previously reported, but not validated, in ovarian cancer cells." (PMID 37971882, 2024). "While not much is known about the clinical implications of WNT5B, high expression of WNT5A has been significantly correlated with ovarian cancer stage, poorer overall survival and poorer progression-free survival." (PMID 34017835, 2021).
asthma (4 papers, 2019 to 2023). "Expression of WNT3, WNT5a, WNT10, and their receptor, Fzd-5, positively correlated with type 2-high asthma in adults whereas expression of WNT5b negatively correlated with type 2 inflammation." (PMID 37814791, 2023). "Asthmatic patients with Wnt regulator (WIF1, WNT5B, and DKK3) enrichment were atopic, had early-onset, long duration, and had severe asthma with the inflammatory profile." (PMID 33791298, 2021).
colon cancer (4 papers, 2018 to 2026). "Caco‐2/Wnt5b cells were induced to migrate and proliferate using Caco‐2 colon cancer cells, while A549 cells were stimulated by Wnt5b exosomes." (PMID 39247621, 2024). "Caco-2 colon cancer cells were used to establish Caco-2/Wnt5b cells with ectopic expression of Wnt5b, whose exosomes also stimulated the migration and proliferation of A549 cells." (PMID 34511114, 2021). "Since we found that Wnt5b is important for proliferation of HCT116 colon cancer cells in β-catenin-independent manner we decided to test whether RoR2 is important for proliferation of these cells as well." (PMID 29453334, 2018). "In a study on the colon cancer, researchers found that KRAS mutations can activate the transcription factor TFCP2, which in turn upregulates the expression of adipogenic factors BMP4 and WNT5B, ultimately inducing CAFs to transform into a special subtype rich in lipids." (PMID 41469334, 2026). "Taken together, our data indicate that Wnt5b promotes proliferation of colon cancer cells via non-canonical, β-catenin independent signaling." (PMID 29453334, 2018).
diabetes (4 papers, 2016 to 2023). "One cohort study in Japanese population found a single nucleotide polymorphism (SNP) site in Wnt5b gene is correlative with risk of diabetes." (PMID 27782077, 2016). "WNT5B regulates both adipocytes and pancreatic cells, two main cell types affected in diabetes, and mis-regulation of WNT5B via this SNP or otherwise in these cell types may lead to disease." (PMID 34017835, 2021).
head and neck squamous cell carcinoma (4 papers, 2011 to 2021). A squamous cell carcinoma that arises from any of the following anatomic sites: lip and oral cavity, nasal cavity, paranasal sinuses, pharynx, larynx, and salivary glands. "Exosomes that are rich in Wnt5b, a protein that is post-translationally glycan- and lipid-modified, have been associated with head and neck squamous cell carcinomas, invasive breast cancer, and lung and pancreatic cancers." (PMID 34576294, 2021).
osteonecrosis (4 papers, 2021 to 2024). A none disease characterized by death of bone tissue due to a lack of blood supply. "In the Steroid-induced osteonecrosis of the femoral head-bone marrow mesenchymal stem cells, five circRNA targeted mRNAs including CLASP1, ENOX2, SYK, UBE2G2, and WNT5B were up-regulated by circRNA42." (PMID 34753940, 2021).
renal fibrosis (4 papers, 2014 to 2026). A final common manifestation of a wide variety of chronic kidney diseases characterized by glomerulosclerosis and tubulointerstitial fibrosis. "Wnt5b knockdown ameliorates hypoxia-induced renal fibrosis in vivo." (PMID 42256303, 2026). "Renal fibrosis developed in C57BL/6 mice following 28 days of hypobaric hypoxia, suggesting Wnt5b involvement in fibrogenesis under hypoxic conditions." (PMID 42256303, 2026). "All members of the WNT protein family (except WNT5b, WNT8b, and WNT9b), β-catenin, Dkk-1, FZD, fibronectin, and MMP-7 were upregulated in the UUO model of renal fibrosis." (PMID 24465439, 2014). "We speculated that Wnt2a, Wnt5b and Wnt9b might not participate in the formation of polycystic kidney lesions and renal fibrosis in the Gpr48 null mice." (PMID 24595031, 2014).
Arthritis (3 papers, 2023 to 2025). Inflammation of a joint. "Thus, this study suggested that circ-PREX1-miR-140-3p-WNT5B axis might be a novel molecular regulation mechanism of paeoniflorin exerting anti-arthritis role in KOA chondrocytes." (PMID 37817257, 2023). "Our results demonstrate that WNT5B may be involved in the dysregulation of AAM, potentially intensifying the inflammatory response observed in arthritis." (PMID 40726988, 2025). "Two patients with arthritis (one with PsA and one with RA) and two with osteoarthritis were excluded because their IHC readings of BMP4 and Wnt5b could not be performed correctly." (PMID 38672170, 2024).
gastric cancer (3 papers, 2016 to 2024). A primary or metastatic malignant neoplasm involving the stomach. "For example, in gastric cancer, WNT5B expression and methylation of its distal DRE (cg02935351) were strongly anti-correlated and WNT5B was predicted to be a tumor suppressor by MRA." (PMID 29871649, 2018). "WNT5B is able to activate calcium signaling and expression of WNT5B was increased in advanced stage gastric cancer and correlated with poor prognosis." (PMID 27391070, 2016). "Therefore, it may be possible to predict the effect of chemotherapy in gastric cancer by WNT5B." (PMID 38952556, 2024). "Current research on WNT5B is not very clear, although it can predict the sensitivity of the epigenetic regulator BET inhibitor iBET-151 to inhibit the growth of gastric cancer, especially when combined with paclitaxel." (PMID 38952556, 2024).
hepatocellular carcinoma (3 papers, 2020 to 2022). A malignant tumor that arises from hepatocytes. "For example, in colon cancer, Wnt5b-associated exosomes promote cancer cell migration and proliferation in a paracrine manner; hepatocellular carcinoma (HCC)-derived exosomes deliver SMAD3 protein and mRNA to detach HCC cells and facilitate their adhesion." (PMID 34205256, 2021). "Namely, Egfr, Vegfb, Wnt2, and Wnt5b, are all genes that play a role in the development or progression of hepatocellular carcinoma." (PMID 35203502, 2022). "Ever report indicated WNT5B could serve as a prognostic biomarker in hepatocellular carcinoma." (PMID 33352742, 2020).
pancreatic cancer (3 papers, 2021 to 2024). "The contribution of WNT5B in exosomes vs. secretion needs to be explored in both pancreatic cancer and other cell types." (PMID 34017835, 2021). "Although WNT5B has not been studied in pancreatic cancer patient samples, WNT5B mRNA is highly expressed in the pancreatic cancer cell line PANC-1." (PMID 34017835, 2021).
prostate carcinoma (3 papers, 2018 to 2022). A carcinoma that arises from epithelial cells of the prostate gland. "Analysis of circulating tumor cells (CTC) revealed that WNT5B is closely associated with prostate cancer." (PMID 31824949, 2019).
triple-negative breast carcinoma (3 papers, 2014 to 2024). An invasive breast carcinoma which is negative for expression of estrogen receptor (ER), progesterone receptor (PR), and human epidermal growth factor receptor 2 (HER2). "WNT5B is upregulated in triple-negative breast cancer patient samples and correlates with a worse prognosis." (PMID 37971882, 2024). "Although WNT5B has been classified as a non-canonical WNT, it activated the canonical WNT pathway in triple negative breast cancer (TNBC) cells." (PMID 30914750, 2019).
breast tumor (2 papers, 2014 to 2015). "Once WNT/β-catenin pathway was identified as a pathway that was triggered by WNT5B, we performed correlation study of WNT5B-related WNT/β-catenin pathway target genes in 884 breast tumor samples; Myc was demonstrated a significant correlation with WNT5B." (PMID 24564888, 2014). "Taken together, our study provided wider insight into the deeper role of WNT5B-triggered WNT/β-catenin signaling; it might regulate breast tumor progression and outcome by modulating mitochondrial physiology through MCL1." (PMID 24564888, 2014).
fibrosis (2 papers, 2022). the formation of excess fibrous connective tissue in an organ or tissue in a reparative or reactive process. "The data indicate that both TGFβ-dependent noncanonical FZD8/Wnt5B signalling and TGFβ-independent canonical β-catenin-dependent signalling may play a role in intestinal fibrosis associated with CD." (PMID 36156078, 2022).
glioblastoma (2 papers, 2022 to 2025). The most malignant astrocytic tumor (WHO grade IV). "To further investigate the effect of FMRP on these mRNAs in glioblastoma, we detected WNT5B and CTNNB1 mRNA levels in an aggressive commercial glioblastoma cell line, namely T98G." (PMID 35982038, 2022).
leukaemia (2 papers, 2019 to 2024). "The immunological signature enrichment revealed the presence of genes, such as BRD3, PBX2, and WNT5B, involved in HSPC proliferation, self-renewal, and differentiation, found deregulated in leukemia." (PMID 31109375, 2019).
lymph node metastases (2 papers, 2021 to 2024). "In our previous report, we observed that the high levels of Wnt5B protein in serum were associated with lymph node metastasis in Taiwanese patients with oral SCC." (PMID 33668218, 2021).
Obesity (2 papers, 2013 to 2021). Accumulation of substantial excess body fat. "This suggestion is supported by the fact that diet-induced obesity resulted in the reduction of Wnt5b expression in adipose tissue." (PMID 23861788, 2013).